SPAAR (small regulatory polypeptide of amino acid response)
Description:
[Isoform 2]: Negative regulator of amino acid sensing and mTORC1, a signaling complex promoting cell growth in response to growth factors, energy levels and amino acids. Negatively regulates mTORC1 activation by inhibiting recruitment of mTORC1 to lysosomes upon stimulation with amino acids: acts by promoting the formation of a tightly bound supercomplex composed of the lysosomal V-ATPase, Ragulator and Rag GTPases, preventing recruitment of mTORC1. Acts as a regulator of muscle regeneration following injury by regulating mTORC1 activation (By similarity).
Synonyms: LINC00961; SPAR
Gene: Protein-coding gene on chromosome 9 (35,909,488 to 35,937,153, forward strand). Ensembl gene ENSG00000235387.
Subcellular location: Late endosome membrane; Lysosome membrane
Gene Ontology:
Biological process: cellular response to amino acid stimulus; negative regulation of TORC1 signaling; regulation of skeletal muscle tissue regeneration
Cellular component: late endosome membrane; lysosomal membrane; lysosomal proton-transporting V-type ATPase complex
Homologues: Orthologues: chimpanzee SPAAR (97% identical), macaque SPAAR (97% identical), pig SPAAR (87% identical), rat Spaar (69% identical), mouse Spaar (65% identical).
Diseases named in the same sentence as SPAAR in open-access papers:
SPAAR is named in the same sentence as 21 diseases in open-access papers, as found by Europe PMC text mining. Sharing a sentence is not in itself a finding about the gene and the disease. The quoted sentences say what the papers report.
non-small cell lung carcinoma (3 papers, 2020 to 2025). A group of at least three distinct histological types of lung cancer, including non-small cell squamous cell carcinoma, adenocarcinoma, and large cell carcinoma. "While the role of the SPAAR microprotein in cancer remains unexplored, recent studies have implicated the LINC00961 transcript itself in tumor suppression in non-small-cell lung cancer (NSCLC)." (PMID 40558487, 2025).
colon cancer (2 papers, 2020). "LINC00961 (SPAAR), located in chromosome 9 (9p13.3), was found to act as a tumor suppressor in various cancers, such as oral squamous cell carcinoma (OSCC), skin melanoma, and colon cancer." (PMID 33024416, 2020).
myocardial infarction (2 papers, 2021 to 2022). Gross necrosis of the myocardium, as a result of interruption of the blood supply to the area, as in coronary thrombosis. "To investigate the influence of the LINC00961/SPAAR locus on longitudinal growth, cardiac function, and response to myocardial infarction, we used a novel CRISPR/Cas9 locus knockout mouse line." (PMID 33478078, 2021).
SPAAR also shares sentences with these, for which no sentence is quoted: tumor (6 papers); cancer (4); breast carcinoma (2); breast invasive carcinoma (2); amyotrophic lateral sclerosis (1); atherosclerosis (1); brain disorder (1); choriocarcinoma (1); depression (1); glioma (1); hepatocellular carcinoma (1); kidney chromophobe (1); oral squamous cell carcinoma (1); pancreatic adenocarcinoma (1); pituitary adenoma (1); serous ovarian cancer (1); skin melanoma (1); tongue tumor (1).